PTPN11 (protein tyrosine phosphatase non-receptor type 11)
Diseases named in the same sentence as PTPN11 in open-access papers (continued):
Sharing a sentence is not in itself a finding about the gene and the disease.
Noonan syndrome (continued). "In addition to the PTPN11 mutations in the RAS‐MAPK signaling pathway, including KRAS, SOS1, RAF1, SHOC2, NRAS, BRAF and CBL, can also cause Noonan syndrome." (PMID 37525886, 2023). "Mutations in the following genes that cause Noonan syndrome have been identified: RAS family GTPase proteins (KRAS, NRAS, RIT1, and RRAS), RAS signal function modulators (PTPN11, SOS1, SOS2, CBL, RASA2, and SHOCS2), and downstream signal transducers (RAF1 and BRAF)." (PMID 38248880, 2023). "Mutations in PTPN11 in human patients cause aberrant signaling of SHP2, resulting in multiple rare hereditary diseases, including Noonan Syndrome (NS), Noonan Syndrome with Multiple Lentigines (NSML), Juvenile Myelomonocytic Leukemia (JMML) and Metachondromatosis (MC)." (PMID 36407105, 2022). "This contrasts with children without Noonan Syndrome bearing somatic RAS mutations in PTPN11, NRAS and KRAS, who account for a significant proportion of JMML cases." (PMID 35409034, 2022). "Noonan syndrome was the first Ras-opathy reported, is the second most common syndromic cause of congenital heart disease, and is associated with mutated genes in the Ras signaling pathway: SHP2 (PTPN11), SOS1, K-Ras or C-RAF among others." (PMID 34344467, 2021). "The most used mouse model to study Noonan syndrome is the Ptpn11 knock-in model." (PMID 34828352, 2021). "In Noonan syndrome, JMML may occur due to PTPN11 germline mutations with similar clinical features to children with JMML arising from PTPN11 somatic mutations, although with a generally better outcome." (PMID 28955657, 2017). "Germline PTPN11 mutations cause Noonan syndrome, therefore this patient may present with RASopathy-related phenotypes given that somatic mutations in FLT3 and PTPN11 activate the Ras/MAPK pathway and are largely mutually exclusive in ALL." (PMID 27683039, 2016). "Thus, we propose that substitutions in Noonan syndrome aberrantly activate the PTPN11 phosphatase by disrupting a phosphorylation-mediated auto-inhibitory loop of the SH2 domain." (PMID 25611800, 2015). "Genetic mutations in PTPN11 exon 3(encoding the N-SH2 domain), exon 4(encoding the C-SH2 domain), Exons 7, 8 and 12(encoding the PTP domain) have been identified in Noonan syndrome, juvenile myelomonocytic leukemia, LEOPARD syndrome, lung cancer, liver cancer and colon cancer." (PMID 22788847, 2012). "Testing for a 22q11.2 microdeletion (DiGeorge syndrome) and a mutation screening in the PTPN11 gene (Noonan syndrome) revealed no mutation." (PMID 19284615, 2009). "Notably, according to the documented medical records at the recruitment, Noonan syndrome had been previously suspected (but not confirmed by genetic testing) for the GEMINI patient carrying an established NS-linked variant PTPN11 p.N58D." (PMID 38654924, 2024). "In addition, cases are described in neurofibromatosis (NF1) and Noonan syndrome (PTPN11)." (PMID 39294363, 2024). "Primary brain and other tumors in Noonan syndrome and other rasopathies with no PTPN11 mutations." (PMID 36060964, 2022). "Other (no hematological) primary tumors in Noonan syndrome with PTPN11 mutations." (PMID 36060964, 2022). "Auxological data and 24hour GH profile measured with polyclonal antibodies in 25 with Noonan syndrome (NS) (with PTPN11 mutation (n=16, without n=9) and in 40 with Turner syndrome (TS) (XO in 31 and 9 either mosaicism or isochromosome), compared to children with normal height (n=45)." (PMID 34858328, 2021).
Noonan syndrome (continued). "Noonan syndrome, Costello, and other similar syndromes characterized by specific dysmorphic features and cardiac involvement with HCM development during infancy are caused by genetic mutations in a set of genes of the RAS-MAPK group (PTPN11, KRAS, SOS1, RAF1, SHP2)." (PMID 32498335, 2020). "We present two cases of Noonan syndrome with external hydrocephalus in the second trimester in the presence of the variations of the SOS1 and PTPN11 genes." (PMID 40507736, 2025). "Noonan syndrome has a wide range of symptoms due to dysregulation of the RAS/MAPK pathway with several gene variations, including the PTPN11 gene." (PMID 40514730, 2025). "In 2001, PTPN11, encoding SHP2, a non-receptor protein tyrosine phosphatase playing a relevant role in intracellular signaling and several developmental processes, was identified as the major Noonan syndrome (NS, MIM: PS163950) disease gene using a positional candidacy approach." (PMID 39336782, 2024). "In another case series, three infants with Noonan syndrome (SOS1, RIT1, PTPN11) all had a reduction in chylous effusions, chylous ascites, and improvement in respiratory status with trametinib therapy." (PMID 38618951, 2024). "SHP2 (PTPN11), an allosteric enzyme involved in RAS–mitogen-activated protein kinase (MAPK) activity, is responsible for Noonan syndrome and is commonly detected in juvenile myelomonocytic leukemias, a condition characterized by errors in blood cell development." (PMID 38132713, 2023). "A missense mutation in the Protein Tyrosine Phosphatase Non-Receptor Type 11 (PTPN11) gene was found in almost 50% of patients diagnosed with Noonan syndrome." (PMID 37441579, 2023). "An analysis of neonatal blood spots has identified such somatic RAS pathway mutations (most commonly in PTPN11, NRAS and KRAS) in 38% of children (n = 34) without Noonan Syndrome but presenting with JMML at a median age of 1.5 years." (PMID 35409034, 2022). "While the majority of those with Noonan Syndrome carry germline mutations in RAS pathway genes (e.g., PTPN11, KRAS, NRAS, SOS-1, RAF1, BRAF), not all develop JMML." (PMID 35409034, 2022). "Similar to NF1, gain of function mutations in protein-tyrosine phosphatase nonreceptor-type 11 (PTPN11, SHP2) enhance ERK signaling in osteoblasts, causing Noonan syndrome associated with impaired skeletal mineralization and short stature." (PMID 35975983, 2022). "Since fibrous osseous dysplasia has been described in cherubism and sporadically in Noonan syndrome, sequencing of exon 9 of the SH3BP2 or KRAS, BRAF and PTPN11 genes was performed, but no pathogenic variant was detected." (PMID 33685999, 2022). "A subset of participants had also been referred for other diagnostic tests, including 22q11 deletion, Down syndrome, CHARGE syndrome (CHD7 sequencing), Noonan syndrome (PTPN11 sequencing) and other conditions, but with no definitive diagnoses." (PMID 32196547, 2020). "Gene sets in protein phosphorylation and JUN-MAPK (mitogen-activated protein kinase) cascades were also enriched but not entirely due to three Noonan syndrome genes (PTPN11, BRAF, RAF1)." (PMID 30532227, 2018). "These heart defects had not been seen in a syndromic context with her retinal changes before genetic testing, and sequencing of PTPN11 and KRAS for suspected Noonan syndrome had revealed no mutation." (PMID 29555955, 2018). "Fifty percent of Noonan syndrome patients and 35% of JMML cases carry gain-of-function mutations in PTPN11 (protein-tyrosine phosphatase, non-receptor-type, 11), altering SHP-2, a tyrosine phosphatase involved in the regulation of the RAS/MAPK pathway." (PMID 28955657, 2017). "The protein-tyrosine phosphatase, non-receptor type 11 (PTPN11; 176,876) gene encodes the non-receptor type protein tyrosine phosphatase SHP-2 (src homology region 2 domain phosphatase–2), which accounts for nearly 50% of cases with Noonan syndrome." (PMID 36496429, 2022).
Noonan syndrome (continued). "Noonan syndrome (NS) and LEOPARD (LS) syndrome are developmental disorders caused by autosomal dominant mutations in PTPN11, which encodes Shp2, a ubiquitously expressed non-receptor protein-tyrosine phosphatase that is involved in numerous signal transduction pathways." (PMID 34095129, 2021). "To investigate the likely tyrosine phosphatase involved, we used blood from patients with Noonan syndrome and an established gain of function mutation in the PTPN11 gene, which encodes for the corresponding protein tyrosine phosphatase non-receptor (also known as SHP2)." (PMID 38236412, 2024). "Likewise, in BAMS, we observed a slight but non-significant decrease in PTPN11 expression (FC −0.69, p-value = 6.01 × 10−06), encoding SHP-2 that binds to PDGFRα and is also associated with facial dysmorphism in Noonan syndrome, further underlining the importance of this signaling pathway in BAMS." (PMID 34209568, 2021). "A small proportion of individuals with Noonan syndrome also exhibit multiple gnathic GCG previously reported as Noonan-like/multiple GCG, but this phenotype is now recognized to be allelic with Noonan syndrome, as mutations in PTPN11, SOS1, and RAF1 have been reported in this syndrome." (PMID 25409853, 2014). "For example, a patient with a pathogenic variant in PTPN11 (MIM #176876) causing Noonan syndrome may have pulmonary stenosis, while a different patient with the same variant may have a different congenital heart disease, or even no heart disease but shows many other Noonan syndrome characteristics." (PMID 39243101, 2024).
leukemia (99 papers, 2007 to 2025). A malignant (clonal) hematologic disorder, involving hematopoietic stem cells and characterized by the presence of primitive or atypical myeloid or lymphoid cells in the bone marrow and the blood. "The overalltranscriptional activities in Ptpn11E76K/+stem cells were elevated compared to those in their WT counterparts, consistent with more active cellular processes in leukemia-initiating Ptpn11-mutatedstem cells." (PMID 39149498, 2024). "In the literature, PTPN11 is notably described for its significant role in leukemia development, where its mutations can lead to hyperactivation, causing proliferation of leukemic cells, therapy resistance, and survival." (PMID 39223638, 2024). "We also demonstrated that all leukemic cells originating in xenografted mice present the leukemia-initiating PTPN11 mutation and stably retain their epigenetic signature." (PMID 37945692, 2024). "PTPN11 mutations have been detected in human cancers including leukemias and solid tumors, with the G503V missense mutation being associated with childhood leukemia and adult acute myelogenous leukemia." (PMID 35625983, 2022). "In vivo mouse models also show cooperation of PTPN11 mutations with KMT2A fusions such as KMT2A-MLLT3 or KMT2A-MLLT10 in leukemia development." (PMID 34944812, 2021). "Germline mutations in the PTPN11 cause Noonan syndrome and somatic mutations occur in leukemia patients." (PMID 34944812, 2021). "PTPN11 mutations have been identified in lung, breast, and colon cancer, leukemia, neuroblastoma, and melanoma." (PMID 30208623, 2018). "We identify acquired de novo mutations in Braf, Cbl, Kras, and Ptpn11 in KMT2A-MLLT3 leukemia cells that favored clonal expansion." (PMID 29720585, 2018). "Mutations of PTPN11 (encoding SHP2) were found in myeloid leukaemia patients (especially childhood leukaemia patients) and some solid tumours." (PMID 29706844, 2018). "Somatic gain of-function mutations of PTPN11 gene have been reported in about half of Noonan syndromes and certain types of leukemias." (PMID 29558404, 2018). "The only recurrently mutated gene was the proto-oncogene tyrosine phosphatase Ptpn11 (encoding Shp-2), acquired in three separate leukemias, Ptpn11E69K (n = 1) and Ptpn11S506W (n = 2)." (PMID 29720585, 2018). "Ptpn11 gain-of-function mutation D61G induces chromosomal instability, resulting in tumorigenesis of leukemia, lymphoma, Lung adenomas, and skin papillomas in mice." (PMID 28085101, 2017). "Different patterns of PAG1 and PTPN11 phosphorylation in leukemia and prostate cancer are associated with different activation states of SFKs and other signaling effectors." (PMID 25884760, 2015). "The E76K mice leukemias were associated with centrosome amplification and aneuploidy, which is highly relevant given the predominance of PTPN11 mutations in hyperdiploid ALL cases." (PMID 25009801, 2014). "Gain of function (GOF) mutations in protein tyrosine phosphatase Ptpn11 have been identified in childhood leukemias, and these mutations are sufficient to drive the development of myeloproliferative disorder and malignant leukemias in mice." (PMID 23675459, 2013). "PTPN11 mutations found in NS and LS are clustered in the PTP domain, whereas most of the leukemia-associated PTPN11 mutations are located in the N-SH2 domain." (PMID 21799948, 2011). "Studies from our laboratory and others have shown that leukemia-associated PTPN11 mutations also enhance multiple other hematopoietic signaling cascades, such as PI3K/AKT and JAK/STAT pathways." (PMID 21799948, 2011). "In leukemia patients, the most prevalent and active PTPN11 variation is the SHP2E76K mutation." (PMID 38504984, 2024). "Mutations in PTPN11 have been linked to the pathogenesis of leukemia and breast cancer." (PMID 36810562, 2023).
leukemia (continued). "Remarkably, as anticipated for NS‐causing and leukemia‐associated PTPN11 mutations, the germline mutations affecting these genes may involve the same residues that represent hot spots in cancer, but the former are generally less activating than the latter." (PMID 36394128, 2022). "Consequently, leukemia engraftment in patient-derived xenograft mice bearing CD34+ TKI-resistant CML blasts carrying PTPN11 mutation responsible for hyperactivation of the RAS/RAF/MAPK and JAK/STAT5 pathways was decreased upon double treatment." (PMID 36460969, 2022). "The identification of PTPN11 mutations in KMT2A-rearranged leukemia and the requirement for SHP2 function in the RAS signaling pathway strongly suggest that small molecule SHP2 inhibitors might have important therapeutic applications." (PMID 31723831, 2019). "However, enrichment was also seen for KMT2A-MLLT3 mouse leukemia with FLT3N676K or Kras/Ptpn11 mutations (MAF 0.39–0.59)." (PMID 29720585, 2018). "Furthermore, activating mutations in PTPN11 gene have also been described in the developmental disorder Noonan syndrome and in pediatric leukemias." (PMID 27582544, 2016). "Furthermore, patients with NS are predisposed to have a higher risk for leukaemia and certain solid tumours, especially if they carry PTPN11 mutations." (PMID 26444854, 2015). "Mutations in the PTPN11 gene have been detected in low frequencies in leukemia cases; however, alterations in this gene predispose patients with Noolan syndrome to several types of leukemia (mainly juvenile myelomonocytic leukemia JMML) and other types of cancer." (PMID 24885312, 2014). "In addition, Ptpn11 disease mutations, especially leukemia/tumor mutations, enhance the binding of mutant Shp2 to signaling partners." (PMID 23675459, 2013). "Furthermore, mutation of SHP2 (PTPN11) has been implicated in leukaemia and other human cancers with increased activity of oncogenic protein tyrosine kinases." (PMID 23185569, 2012). "Notably, identified de novo mutations influenced the GEP for samples with mutations in the dominant leukemia clone, i.e., Kras and Ptpn11 (MAF 0.39–0.59), now clustering closely to those with a constitutively expressed mutation; this was not seen for mutations with MAF ≤ 0.30." (PMID 29720585, 2018). "Juvenile myelomonocytic leukemia (JMML) is a deadly pediatric leukemia driven by RAS pathway mutations, of which >35% are gain-of-function in PTPN11." (PMID 37958378, 2023). "Next-generation sequencing (NGS) targeting 172 leukemia- and lymphoma-related genes identified ANKRD26-p.Asn267Ser, PTPN11-p.Glu76Lys, CIITA-p.His1119Asn and FAT1-p.Phe765Tyr mutations." (PMID 35912172, 2022). "Probably, the most common alterations in leukaemia are those found in the RAS/MAPK pathway (50% of relapsed B-ALL, 15% of T-ALL and 50% of AML), such as KRAS, NRAS and PTPN11 mutations." (PMID 35743666, 2022). "In our research, we discovered that PTPN11 is a hub protein that is involved in numerous forms of leukemia and hepatic carcinogenesis." (PMID 36314741, 2022). "SH2 domain-containing protein tyrosine phosphatase 2 (SHP2), encoded by PTPN11, is associated with a number of malignant conditions, including breast cancer, leukemia, lung cancer, liver cancer, gastric cancer, and other cancer types." (PMID 32936431, 2020). "It is an intriguing candidate because PTPN11 is mutated in Noonan and LEOPARD syndromes and activating mutations have been implicated in the pathogenesis of leukemia while inactivating mutation promotes the development of hepatocellular carcinoma." (PMID 24454681, 2014). "Notably,Ptpn11E76K/+ mutant HSCs(leukemia-initiating cells) and GMPs exhibited reduced abundance, while monocytes andneutrophils displayed an increase compared to their WT(Ptpn11+/+) counterparts." (PMID 39149498, 2024).